ROBO4 (roundabout guidance receptor 4)
Description:
Receptor for Slit proteins, at least for SLIT2, and seems to be involved in angiogenesis and vascular patterning. May mediate the inhibition of primary endothelial cell migration by Slit proteins (By similarity). Involved in the maintenance of endothelial barrier organization and function.
Synonyms: FLJ20798; MRB; ECSM4; AOVD3
Tractability: Antibody: UniProt predicts a signal peptide or a membrane-spanning region; its Gene Ontology location is reachable by antibodies, with medium confidence; the Human Protein Atlas places it where antibodies can reach.
Gene: Protein-coding gene on chromosome 11 (124,883,666 to 124,898,500, reverse strand). Ensembl gene ENSG00000154133.
Subcellular location (Human Protein Atlas): Plasma membrane
Gene Ontology:
Molecular function: protein binding; cell-cell adhesion mediator activity; signaling receptor activity
Biological process: angiogenesis; establishment of endothelial barrier; axon guidance; dendrite self-avoidance; homophilic cell-cell adhesion; regulation of cell migration
Cellular component: extracellular exosome; axon; membrane; plasma membrane; external side of plasma membrane
Genetic constraint (gnomAD): Loss-of-function variants: 81 observed, 106.67 expected, observed/expected ratio (o/e) 0.76, 90% interval 0.63 to 0.91. The upper end of that interval is the gene's LOEUF score, 0.91, which puts it in group 3 of 6, group 1 being the genes least tolerant of losing a copy. Missense variants: 1,333 observed, 1,323.2 expected, observed/expected ratio (o/e) 1.01, 90% interval 0.96 to 1.05. Synonymous variants: 504 observed, 544.49 expected, observed/expected ratio (o/e) 0.93, 90% interval 0.86 to 1.
Homologues: Orthologues: chimpanzee ROBO4 (99% identical), macaque ROBO4 (95% identical), dog ROBO4 (84% identical), pig ROBO4 (84% identical), guinea pig ROBO4 (80% identical), rat Robo4 (78% identical), mouse Robo4 (77% identical), rabbit ROBO4 (72% identical). Paralogues in human: ROBO1 (20% identical), ROBO2 (20% identical), ROBO3 (20% identical), SDK2 (19% identical), DCC (18% identical), CNTN4 (17% identical), SDK1 (17% identical), IGSF10 (17% identical), NRCAM (17% identical), CNTN2 (17% identical), MXRA5 (17% identical), HMCN2 (17% identical), and 24 more.
Diseases named in the same sentence as ROBO4 in open-access papers:
ROBO4 is named in the same sentence as 66 diseases in open-access papers, as found by Europe PMC text mining. Sharing a sentence is not in itself a finding about the gene and the disease. The quoted sentences say what the papers report.
glioma (5 papers, 2016 to 2022). A benign or malignant brain and spinal cord tumor that arises from glial cells (astrocytes, oligodendrocytes, ependymal cells). "Recently, it has been shown that higher Robo4 expression levels in gliomas and also acute myeloid leukemias are associated with shorter overall survival." (PMID 26956051, 2016). "Different types of glioma-conditioned medium stimulated EC proliferation, migration and tube formation and decreased Robo4 expression, and overexpression of Robo4 suppressed these effects." (PMID 31160487, 2019). "Slit2 expression was also down-regulated in grade III–IV glioma tissues, and the viability, migration and tube formation of ECs were significantly reduced in the Robo4 overexpression group that was pretreated with exogenous Slit2." (PMID 31160487, 2019). "Accordingly, Robo4 inhibits glioma-induced EC proliferation, migration and tube formation by binding to its ligand Slit2, and thus, the first Robo4 targeting strategy is the injection of high doses of the recombinant Slit2 protein." (PMID 31160487, 2019). "For the downregulated genes in the combination treated tissue compared with the Ad-SGE-REIC-treated U87ΔEGFR glioma tissue, seven significantly enriched pathways were identified, including the Robo4 and VEGF Signaling Pathways Crosstalk and TNF-alpha NF-kB Signaling Pathway." (PMID 36006934, 2022). "In addition, SLIT3 interacts with Robo4 to induce tumor angiogenesis, SLIT3 is a glycoprotein that guide axonal development during embryogenesis and cell migration that is frequently hypermethylated and silenced in lung, breast, colorectal and glioma cell lines and primary tumors." (PMID 27355345, 2016).
lung cancer (5 papers, 2014 to 2025). A malignant neoplasm involving the lung. "In comparison to, 9 variants in ROBO1, variants in ROBO4, and 34 variants from the non-lung cancer dataset were found." (PMID 33318575, 2020). "Out of 825 variants; 34 in ROBO1, 57 in SLIT2, and 34 in ROBO4 were reported to be associated with lung cancer." (PMID 33318575, 2020). "In comparison, the other 255 variants in ROBO1, 324 variants in SLIT2 and 121 variants in ROBO4 were considered as non-lung cancer dataset." (PMID 33318575, 2020). "Similarly, for outside the docking domains, 3 variants of ROBO1 and 2 variants of ROBO4 show inter-orbital shift of mutant amino acid residue compared to wild type residue in the lung cancer dataset." (PMID 33318575, 2020). "Both Slit2-WT and Slit2-ΔE15 inhibit lung cancer cell invasion, but Robo4 is essential for Slit2-WT-mediated invasion inhibition in CL1-5 cells, while neither Robo1 nor Robo4 is required for Slit2-ΔE15-mediated invasion inhibition." (PMID 41227302, 2025). "About, 0.4% of ROBO1, 0.8% of ROBO4, and 2% of SLIT2 variants of non-lung cancer dataset were predicted to be associated with "cancer" by FATHMM." (PMID 33318575, 2020). "PolyPhen243 predicted about 15% of ROBO1, 15% of ROBO4, and 23% of SLIT2 variants of lung cancer dataset to be "possibly damaging"." (PMID 33318575, 2020). "About 25% of ROBO1, 25% of ROBO4, and 35% of SLIT2 variants of non-lung cancer dataset were predicted to be "Disease-related" by SNPs&GO." (PMID 33318575, 2020). "About 61% of ROBO1, 45% of ROBO4, and 61% of SLIT2 variants of non-lung cancer dataset were predicted to be "damaging" by SIFT." (PMID 33318575, 2020). "About 89% of ROBO1, 76% of ROBO4, and 83% of SLIT2 variants of non-lung cancer dataset were predicted to cause a "decrease" in protein stability." (PMID 33318575, 2020). "From the non-lung cancer dataset, 113 variants of ROBO1, 134 variants of SLIT2 and 41 variants of ROBO4 were selected for structure-based analysis." (PMID 33318575, 2020). "Steric clash-induced destabilisations, primarily found in variants involving bulky amino acids were 7 in ROBO1, 5 in ROBO4 and 9 in SLIT2 from the lung cancer dataset." (PMID 33318575, 2020). "The variants were analysed in PROVEAN41 that predicted nearly 50% of ROBO1, 29% of ROBO4, and 63% of SLIT2 variants of lung cancer dataset to be "deleterious"." (PMID 33318575, 2020). "Our study is the first report that involves the characterisation of somatic variants of ROBO1.IG1, ROBO4.IG1-2 and SLIT2.D2 domains reported in various cancers including lung cancer, and their role in domain-domain interactions of the receptors (ROBO1.IG1 and ROBO4.IG1-2) and the ligand (SLIT2.D2)." (PMID 33318575, 2020). "Interestingly, iMUTANT 2.0 revealed 91% of ROBO1, 79% of ROBO4, and 84% of SLIT2 variants of lung cancer dataset to cause a "decrease" in protein stability." (PMID 33318575, 2020). "Thus, from the lung cancer dataset, 18 variants of ROBO1, 29 variants of SLIT2 and 13 variants of ROBO4 were selected for structure-based analysis." (PMID 33318575, 2020). "However, 2 variants of ROBO1.IG1, 2 variants of SLIT2.D2 and 1 variant of ROBO4.IG1-2 domains in lung cancer dataset and 6 variants in SLIT2.D2 in the non-lung cancer dataset exhibits an intra-orbit amino acid position shift compared to wild types." (PMID 33318575, 2020). "Similarly, in the non-lung cancer dataset, 5 variants of ROBO1.IG1, 7 variants of SLIT2.D2 and 2 variants of ROBO4.IG1-2 domains show an inter-orbit shift of mutant amino acid compared to wild types." (PMID 33318575, 2020). "The details of the molecular interaction of ROBO4.IG1-2 with SLIT2.D2 in our study could provide shreds of evidence for the ROBO4 mediated angiogenesis in lung cancer pathogenesis." (PMID 33318575, 2020). "Similarly, analysis in SIFT42 revealed about 65% of ROBO1, 47% of ROBO4, and 60% of SLIT2 variants of lung cancer dataset to be "damaging"." (PMID 33318575, 2020).
lung cancer (continued). "Similarly, 40% of ROBO1, 18% of ROBO4, and 56% of SLIT2 variants of non-lung cancer dataset were predicted to be "deleterious" by PROVEAN." (PMID 33318575, 2020). "Finally, for the interacting domains, the prioritisation analysis revealed 2 variants of ROBO1, 2 variants of ROBO4 and 3 variants of SLIT2 in lung cancer dataset and 6 variants of ROBO1, 2 variants of ROBO4 and 15 variants of SLIT2 from the non-lung cancer dataset as depicted in." (PMID 33318575, 2020). "However, our group has previously found that higher TEM expression levels (Robo4, ECSCR, Clec14) correlated with a prolonged overall survival in primary lung cancer tumor samples." (PMID 26956051, 2016). "In a study investigating gene expression patterns in non-smoking lung cancer patients, researchers identified ROBO4 and TEK as down-regulated genes compared to healthy individuals, suggesting a potential role for these genes in the development or progression of lung cancer in non-smokers." (PMID 39595659, 2024).
Sepsis (5 papers, 2014 to 2024). Sepsis is defined as life-threatening organ dysfunction caused by a dysregulated host response to infection. "ROBO4 has been shown to ameliorate multiple diseases in mice, including infectious diseases and sepsis." (PMID 38762541, 2024). "Also, a novel anti-inflammatory strategy (apoA-I mimetic 4F) that increased Robo4/Slit2 expression strengthened vascular barrier function, protecting kidneys and heart in an animal model of sepsis." (PMID 25360813, 2014). "Robo4 is an important inhibitor of pathologic angiogenesis and endothelial hyper-permeability, that prevented VEGF-induced changes in models of retinal and choroidal vascular disease; and hyper-permeability in bacterial and viral models of sepsis." (PMID 25360813, 2014).
diabetes (4 papers, 2019 to 2024). "In the pathological environment of diabetes mellitus, the expression of ROBO4 is abnormally increased and excessive ROBO4 accelerates the development of DR, as confirmed in our previous studies." (PMID 37430272, 2023). "Western blotting showed high levels of HIF‐1α, SP1 and ROBO4 after 4 weeks of uncontrolled diabetes, with levels sustained at 6 and 8 weeks." (PMID 31094072, 2019). "Moreover, TET2 can regulate the expression of ROBO4 and its downstream proteins through active demethylation of the ROBO4 promoter, thereby accelerating the development of retinal vasculopathy in diabetes." (PMID 38172938, 2024). "In diabetes, TET2 can regulate the expression of ROBO4 and its downstream proteins by mediating active demethylation of the ROBO4 promoter, which accelerates the development of retinal vasculopathy." (PMID 37430272, 2023). "As the duration of uncontrolled diabetes was prolonged, VEGF and Robo4 expression were enhanced and sustained at a high level in the retinas during the DR progression." (PMID 30980286, 2019).
leukemia (4 papers, 2015 to 2023). A malignant (clonal) hematologic disorder, involving hematopoietic stem cells and characterized by the presence of primitive or atypical myeloid or lymphoid cells in the bone marrow and the blood. "High expression levels of ROBO3 and ROBO4 RNA were noted in poor Cancer and Leukemia Group B (CALGB) cytogenetic risk group of patients in comparison with normal and favorable risk groups (p = 0.0029 and p = 0.0003, respectively, from ANOVA-Kruskall–Wallis test)." (PMID 30820596, 2019). "Like CD34‐positive leukemia‐initiating AML cells we find ROBO4 significantly overexpressed in CD34‐positive ALL samples, but we also find other axonal growth guidance genes upregulated, such as EFNB1 and EPHA7." (PMID 35271751, 2022). "Higher BM Robo4 expression were positively associated with the expression of HLA-DR (P<0.0001), CD13 (P = 0.0417), CD34 (P = 0.0009) and CD56 (P = 0.039) on the leukemia cells." (PMID 25794001, 2015). "Expression of Robo4 was recently found in solid tumors and leukemia stem cells." (PMID 25794001, 2015). "In addition to vasculoendothelial cells, Robo4 protein staining could be clearly seen in leukemia cells in the BM with a high score." (PMID 25794001, 2015).
acute myeloid leukemia (3 papers, 2015 to 2019). Acute myeloid leukemia (AML) is a group of neoplasms arising from precursor cells committed to the myeloid cell-line differentiation. "Patients with acute myeloid leukemia (AML) presenting high Robo4 expression have a significantly shorter disease-free survival (DFS) and overall survival (OS) than patients with lower Robo4 expression." (PMID 31160487, 2019). "However, the clinical implications of Robo4 expression in patients with acute myeloid leukemia (AML) remain unclear." (PMID 25794001, 2015).
colorectal cancer (3 papers, 2015 to 2024). A primary or metastatic malignant neoplasm that affects the colon or rectum. "Robo4, a receptor for Slit2, is highly expressed in solid tumors, including brain, lung, urinary bladder and colorectal cancers and its expression is restricted to tumor vasculature but down-regulated in mature vasculature." (PMID 25794001, 2015). "Other pathways identified were Beta‐catenin‐dependent transcription regulation in colorectal cancer; Development_ROBO2, ROBO3, and ROBO4 signaling pathways, Notch signaling in oligodendrocyte precursor cell differentiation in multiple sclerosis and Signal transduction_mTORC1 upstream signaling." (PMID 36329628, 2023).
diabetic retinopathy (3 papers, 2019 to 2023). "According to earlier research, specificity protein 1 (SP1) enhances the binding to the ROBO4 promoter, increasing Robo4 expression and hastening the progression of diabetic retinopathy." (PMID 37430272, 2023). "Roundabout 4 (ROBO4) is involved in angiogenesis, which varies with the development of diabetic retinopathy (DR)." (PMID 31094072, 2019). "We have previously found that the expression of ROBO4 was elevated in diabetic retinopathy." (PMID 37430272, 2023).
Hyperglycemia (3 papers, 2019 to 2023). An increased concentration of glucose in the blood. "Inhibition of the SP1/ROBO4 pathway significantly ameliorated hyperglycemia-induced HRECs dysfunction." (PMID 37430272, 2023). "A similar trend was observed in the western blotting assay, where TET2 shRNA transfection downregulated the hyperglycemia-induced elevated ROBO4 and TET2 protein expression levels." (PMID 37430272, 2023). "We found that hyperglycemia upregulated the transcript levels of ROBO4, DNMT1 and TET2, in an exposure time-dependent manner." (PMID 37430272, 2023). "Previous studies have shown that there are two binding sites for SP1 in the ROBO4 promoter in HRECs, and that SP1 binding activity to ROBO4 was enhanced in hyperglycemia." (PMID 37430272, 2023). "Consistent with mRNA changes, the protein levels of VEGF were elevated in HREC and RPE cells exposed to hyperglycemia, with the downregulation of Robo4." (PMID 30980286, 2019). "Here, we assessed the roles of miR‐125b‐5p and miR‐146a‐5p in HIF‐1α/SP1‐mediated ROBO4 expression in vivo in diabetic rats or in vitro in RPE cells under hyperglycaemia or hypoxia." (PMID 31094072, 2019). "Robo4 decreased in ARPE-19 tissue culture cells exposed to hyperglycemia for 72 h, whereas it increased in diabetic rat retinas." (PMID 30980286, 2019). "Knockdown of HIF‐1α significantly inhibited SP1 and ROBO4, whereas SP1 down‐regulation abolished ROBO4 expression in RPE cells under hyperglycaemia/hypoxia." (PMID 31094072, 2019). "Additionally, after inhibiting TET2 expression by shRNA, the oxidation of 5mC to 5hmC and SP1 binding to ROBO4 decreased, which regulated the abnormal hyperglycemia-induced increase in ROBO4 and returned ROBO4 expression to almost normal levels." (PMID 37430272, 2023). "Our previous studies have also demonstrated that ROBO4 depletion may partially protect against hyperglycemia-induced HREC dysfunction." (PMID 37430272, 2023). "Furthermore, the effect of hyperglycemia on the binding activity of TET2 to the ROBO4 promoter in HRECs was detected by ChIP." (PMID 37430272, 2023). "Nevertheless, Robo4 expression decreased in HREC or RPE under hyperglycemia." (PMID 30980286, 2019). "Thus, HIF‐1α, SP1 and ROBO4 had important regulatory roles in RPE cells under hyperglycaemia or hypoxia." (PMID 31094072, 2019). "Thus, inhibition of SP1/ROBO4 under hyperglycaemia or HIF‐1α/ROBO4 under hypoxia reduced cell motility." (PMID 31094072, 2019). "The suppressive effects of specific siRNAs on hyperglycaemia‐induced HIF‐1α, SP1, and ROBO4 up‐regulation were also observed by Western blotting." (PMID 31094072, 2019). "Considering that VEGF was enhanced and Robo4 was inhibited in HREC and RPE cells under hyperglycemia, we focused on analyzing miR-15a, miR-16, and miR-424." (PMID 30980286, 2019). "This prediction verified that, when HREC and RPE cells were exposed to hyperglycemia, enhanced VEGF inhibited Robo4 via the downregulation of miR-15a." (PMID 30980286, 2019). "MicroRNA (miRNA)-mediated modulation of VEGF and Robo4 was explored in diabetic rats and ARPE-19 tissue culture cells under hyperglycemia." (PMID 30980286, 2019). "Moreover, this transfection reduced hyperglycaemia‐induced SP1 and ROBO4 up‐regulation at both mRNA and protein levels." (PMID 31094072, 2019). "Additionally, HIF‐1α, SP1 and ROBO4 levels were elevated concomitantly in vivo in a model of DR and in vitro in RPE cells cultured under hyperglycaemia or hypoxia." (PMID 31094072, 2019). "Additionally, in vitro experiments confirmed the increased expression of ROBO4 in ARPE‐19 cells in response to hyperglycaemia or hypoxia and showed that ROBO4 was localized in RPE cells under hyperglycaemia." (PMID 31094072, 2019). "Additionally, HIF‐1α, SP1 and ROBO4 co‐expressed in the diabetic retina and in RPE cells under hyperglycaemia." (PMID 31094072, 2019).
Hyperglycemia (continued). "The effects of hyperglycemia on DNA methyltransferase 1, Tet methylcytosine dioxygenase 2 (TET2), 5-methylcytosine, 5-hydroxymethylcytosine, and the binding of TET2 and SP1 to the ROBO4 promoter, as well as the expression of ROBO4, zonula occludens 1 (ZO-1) and occludin were examined." (PMID 37430272, 2023). "However, under hyperglycaemia, SP1 siRNA, ROBO4 siRNA and miR‐125b‐5p could protect against HG‐stimulated RPE migration, and HIF‐1α siRNA, ROBO4 siRNA and miR‐146a‐5p could also prevent hypoxia‐induced RPE migration." (PMID 31094072, 2019).
aneurysm (2 papers, 2021 to 2023). Bulging or ballooning in an area of an artery secondary to arterial wall weakening. "The ROBO4: p.(Ala303Asp) has been identified in a pediatric BAV-case (BAV-PED-7) with aneurysm." (PMID 36855159, 2023). "Recently, mutations in the gene ROBO4, which codes for Roundabout homolog 4 (ROBO4), have been identified in patients with BAV and aneurysm of the ascending aorta; these mutations are predicted to interfere with ROBO4′s function in the modulation of endothelial to mesenchymal transition." (PMID 33514025, 2021).
congenital diaphragmatic hernia (2 papers, 2019 to 2022). A posterolateral defect of the diaphragm that allows passage of abdominal viscera into the thorax, leading to respiratory insufficiency and persistent pulmonary hypertension with high mortality. "Three genes located at 11q24.2 region, ROBO3, ROBO4, and CDON, are possible candidate genes for congenital diaphragmatic hernia." (PMID 35440058, 2022).
COVID-19 (2 papers, 2024). A disease caused by infection with severe acute respiratory syndrome coronavirus 2. "In addition, our recent findings indicate that small molecules that enhance ROBO4 expression suppress vascular permeability and mortality in mouse endotoxemia and COVID-19 models." (PMID 38762541, 2024).